CXCR4 (C-X-C motif chemokine receptor 4)
Diseases named in the same sentence as CXCR4 in open-access papers (continued):
Sharing a sentence is not in itself a finding about the gene and the disease.
infection (continued). "Thus, as infection progresses, new Env variants are able to infect cells that express CXCR4 with limited amounts of CD134, such as naïve B cells and CD8 T cells." (PMID 22163340, 2011). "The restricted expression of CCR5 mainly on memory CD4+ T cells, but broader expression of CXCR4 on both memory and naïve subsets, is thought in part to underlie the accelerated disease progression seen in individuals in whom CXCR4-using HIV-1 variants emerge late in the course of infection." (PMID 20865163, 2010). "Thus, the emergence of HIV-1 viruses that can utilize CXCR4 as a coreceptor typically exposes a much larger population of CD4-positive T lymphocytes to potential infection by HIV-1 and is usually associated with a poorer prognosis." (PMID 20967243, 2010). "Persistent depletion of mucosal CD4+ T cells expressing CCR5 and CCR5/CXCR4, the cells that are targeted during acute and early infection, may perhaps be a consequence of HIV-1 associated cytopathicity and/or nonspecific immune activation and apoptosis." (PMID 17147468, 2006). "In this study, we investigated the impact of a CXCR4 antagonist on the pathogenic phenotypes seen in patients with chronic neutropenia, including abnormalities in blood and BM neutrophil levels, as well as infection susceptibility, in a pharmacologically induced CXCR2 LOF mouse model." (PMID 41451234, 2025). "Moreover, virus co-receptor expression by mast cells might be influenced by IgE-FcεRI interactions, thus establishing their susceptibility to infection with CXCR4-tropic and R5X4-tropic variants." (PMID 34440163, 2021). "Knowing that virus-induced inflammation in animal models and humans is associated with an increase in serum levels of G-CSF, a decreased local concentration of CXCL12 in the bone marrow may have been why VSV caused the otherwise unexpected release of CXCR4+ neutrophils by 24-h post-infection." (PMID 32882969, 2020). "Furthermore, recent studies have shown that the mechanism for infection of some variants of the highly mutable HIV virus may heavily rely on the C-X-C chemokine receptor type 4 (CXCR4) co-receptor." (PMID 32850447, 2020). "The relative infection efficiencies of CXCR4- and CCR5-using viruses may underlie this difference." (PMID 28484447, 2017). "It must be noted, however, that a preferential selection of the X4 variants in CCR5 Δ32/wt cases is also possible; to date, there is no conclusive data on whether the presence of the Δ32 allele is associated with lower susceptibility to R5 infections or favours a switch to CXCR4 using clades." (PMID 26297538, 2015). "Our data suggest that the variants that emerged late in the infection of cat A613 have a reduced ability to infect diverse cells types and that this may stem from alterations in the way they interact with the viral receptors CXCR4 and CD134." (PMID 23372784, 2013). "Therefore, our data carefully raise the possibility that the emergence of CXCR4 using HIV-1 variants during infection, might at least in part be also driven by increased expression of tetherin on the target cells." (PMID 20078884, 2010). "Additionally, in the natural infection of subtypes A, B, D and A/E, a positive correlation was identified between increasing positive charge of the V3 loop and loss of the V3 glycosylation site both of which are expected to promote CXCR4 usage." (PMID 18328091, 2008). "However, over-expression of CXCR4 alone is sufficient to render cells susceptible to infection with some strains of FIV, suggesting that such strains of virus may have a propensity to adaptation in cell culture to CD134-independence." (PMID 18721458, 2008). "In addition, we included a selected subset of samples from SHIVKu1-infected macaques in order to compare the differences between the extent of CC-chemokine down-regulation caused by CCR5-tropic SHIVSF162P4 and more pathogenic CXCR4-tropic SHIVKu1 at the acute stage of infection." (PMID 17684570, 2007).
infection (continued). "Mathematical modeling of HIV evolution, phylogenetic analyses, and viral quasi-species complexity indices showed that infection with CXCR4-using viruses is most often initiated by one, occasionally two variants, similar to R5 viruses." (PMID 42132422, 2026). "Here, we found that transmitted CXCR4-using Envs shared with R5 Envs common genetic and functional determinants, demonstrating their potential to transmit infection." (PMID 42132422, 2026). "In this assay, either CXCR4- or CCR5-tropic HIV-1 virions that contain β-lactamase protein (BlaM) fused to Vpr (BlaM-Vpr) are used for MDDCs infection." (PMID 40029073, 2025). "The CXCR4 expression retains a monocyte precursor in the bone marrow, which replenishes the peripheral mature monocyte pool during infections." (PMID 40241761, 2025). "In naïve CD4+ T cells, Tat increases the expression of the HIV-1 co-receptors CXCR4 and CCR5 while blocking the function of CXCR4, which increases the susceptibility of these cells to infection by HIV-1 variants with R5 tropism." (PMID 40358148, 2025). "Nevertheless, the most efficient combination for infection either Env-753Stop or Env-WT cells remained the CD4-GPI plus CXCR4-318 combination." (PMID 40284914, 2025). "HIV-1LAI is a CXCR4 tropic strain unable to infect macrophages whereas HIV-1NL4.3-BaL uses CCR5 as a co-receptor which is a requirement for infection of macrophages." (PMID 39229127, 2025). "In the transition process of the virus, HIV-1 envelope glycoprotein interacts with the primary receptor CD4 and coreceptor CCR5 or CXCR4 to enter the host cells and produce the infection." (PMID 41181130, 2025). "At 4 weeks post-infection, half of the latently infected huNSG mice were treated with a reactivation cocktail consisting of G-CSF and the CXCR4 antagonist AMD3100 to induce cellular differentiation and mobilization." (PMID 39655954, 2025). "M-CSF secreted by the infected cells then renders the incoming monocytes/macrophages more susceptible to infection by facilitating cell differentiation, enhancing expression of CD4, CCR5, and/or CXCR4 and potentially affecting virus replication after entry." (PMID 40507836, 2025). "Based on previous observations of fusion in reverse, we tested CD4 and CXCR4 variants for their abilities to be assembled into HIV-1-based lentivirus vectors and accomplish fusion in reverse infections." (PMID 40284914, 2025). "For instance, in infection models, TLR2 facilitates CXCR4 expression and function through physical co-association and cross-talk, enhancing downstream signaling that promotes migration and inflammation." (PMID 41451130, 2025). "Because Cxcr4−/− is embryonically lethal, we utilized a ROSA-CreERT x Cxcr4fl/fl mouse system to induce deletion of Cxcr4 prior to infection by administering tamoxifen; brain, cervical lymph nodes, and spleen were harvested 8 dpi." (PMID 40581668, 2025). "As before, we observed increased infection with our CXCR4-tropic NL4–3 strain at day 5 post-infection in the CPSF6 knock-out cells." (PMID 41385587, 2025). "Neither the lab-adapted CCR5-tropic viruses nor the VSV-G pseudotyped virus showed a significant increase in infection, suggesting that that increased CXCR4 expression is the major driver of enhanced CXCR4-tropic virus permissivity in these cells." (PMID 41385587, 2025). "For both the CCR5 and CXCR4 viruses, the exponential phase of virus replication begins at 24 h after infection." (PMID 38504093, 2024). "Previous studies have demonstrated that EBV downregulates CXCR4, a classic DZ biomarker, in early stages of infection." (PMID 38059622, 2024). "The two coreceptors involved in the infection are CXCR4 (chemokine receptor 4 α) and CCR5 (chemokine receptor 5 β), which play crucial roles in the evolution of infection." (PMID 38920978, 2024).
infection (continued). "As we observed a decrease in syncytia formation in both the polyclonal and clonal cell lines, we suspected that CXCR4 expression was responsible for the significantly decreased infection observed in the JunB KO 1–6 cells." (PMID 38835488, 2024). "As the infection progresses, CXCR4 usage becomes more prevalent, correlating with a more rapid decline in CD4+ T‐cell counts." (PMID 39319247, 2024). "WHIM (warts, hypogammaglobulinemia, infections, and myelokathexis) syndrome is an autosomal dominant primary immunodeficiency caused by GOF mutations of CXCR4." (PMID 38519141, 2024). "The phenotype resulted from downregulation of CXCR4, as infection levels were recovered by reintroduction of CXCR4 in JunB KO cells." (PMID 38835488, 2024). "Surface CD4 and CXCR4 expression was demonstrated to be equivalent at the time of infection in control or SLFN14 cells by flow cytometry, and cell supernatant HIV-1 p24 levels were normalized to the % of CD4/mCherry CXCR4 double positive cells." (PMID 38675845, 2024). "The CRISPR-Cas9 system has proven effective in editing CXCR4 and protecting these cells from infection by X4-tropic HIV strains." (PMID 39459922, 2024). "As previously reported, at a steady state (pre-infection), WHIM mice carrying one or two CXCR4 mutations suffer from panleukopenia and had significantly lower counts of white blood cell counts (WBC), neutrophils and lymphocytes in their blood." (PMID 39226327, 2024). "During the late symptomatic stage of HIV-1 disease, when CXCR4-utilizing HIV strains are most predominant, then the infection dynamics shift whereby Th2 cells are mostly infected by CXCR4-utilizing viruses." (PMID 38255719, 2024). "HIV-1 typically uses CCR5 as the coreceptor with CXCR4-usage occasionally evolving late in the course of infection." (PMID 38422171, 2024). "In contrast, the decrease in CXCR4 expression in the clonal JunB KO 1–6 cells was substantial enough to significantly inhibit infection." (PMID 38835488, 2024). "While these population-level effects are strong, data at the single-cell level indicate that subsets of EBV-infected cells in both early infection and LCLs retain or upregulate DZ mRNA for CXCR4, FOXO1, AICDA, IL2RB, AURKC, and LMO2." (PMID 38059622, 2024). "HIV-1 usually utilizes CCR5 as its coreceptor and rarely switches to a CXCR4-tropic virus until the late stage of infection." (PMID 36821374, 2023). "At the same time, because of the flexible CXCR4 ligand binding surface able to accommodate residual chirality or conformational changes, HIV-1 can still retain its ability to recognize an important host cell receptor such as CXCR4 for entry and infection." (PMID 37243169, 2023). "CXCR4-tropic viruses emerge during later stages of infection in approximately 50% of people living with HIV (PLWH) that do not take antiretroviral therapy (ART)." (PMID 36821374, 2023). "For CXCR4-tropic infection, a total of 15,485 cells were analyzed, of which 10,891 did not have detectable HIV RNA, and 4,346 had low levels of RNA expression (248 cells had high levels of RNA expression and were excluded)." (PMID 38156317, 2023). "As expected, infection with the CCR5 virus was less frequent compared to infection with the CXCR4 virus (p-value < 0.001)." (PMID 38156317, 2023). "Because infection with CCR5-tropic virus is less efficient in vitro compared to CXCR4-tropic infection, we first evaluated the proportions of cells infected with viruses of different tropisms." (PMID 38156317, 2023). "Briefly, we observed higher virulence of CXCR4-tropic strains as opposed to CCR5-tropic strains, as well as the preferential infection of thymocytes by CXCR4-tropic strains." (PMID 37111494, 2023). "Seven hundred ninety-four genes were identified for the 10-day model set from Experiment #1, 142 genes were identified for CXCR4-tropic infection, and 278 genes for CCR5-tropic infection in Experiment #2." (PMID 38156317, 2023).
infection (continued). "The envelope (Env) glycoprotein of human immunodeficiency virus type-1 (HIV-1) is the virus attachment protein that interacts with the host-cell receptor CD4 and chemokine receptors CCR5 or CXCR4 to initiate infection." (PMID 37681958, 2023). "Despite high expression of CCR5 and CXCR4 by tTregs, FoxP3 + CD3highCD8- thymocytes were much less prone to in vitro infection with R5- and X4-tropic HIV strains compared to FoxP3-CD3highCD8- thymocytes." (PMID 37547675, 2023). "Conventional HIV infection involves virus binding to the CD4 receptor, followed by interaction with co-receptors such as CCR5 or CXCR4 on CD4+ T lymphocytes to initiate direct infection or cis infection." (PMID 37808906, 2023). "Of note, in this experiment, an order of magnitude fewer genes were identified for CXCR4-tropic infection, compared to the set described in Experiment #1 that assessed the effect of environmental stimuli." (PMID 38156317, 2023). "The TZM.bl cells used for neutralization assays are HIV-1 permissive reporter HeLa cells modified to express the receptor (human CD4) and co-receptors (human CCR5 and CXCR4), allowing the virus to initiate infection in these cells." (PMID 37681958, 2023). "CCR5 is dominant in the acute infection and asymptomatic phase, whereas CXCR4 is related to progression of the disease." (PMID 35372102, 2022). "Still, efficient infection of peripheral blood mononuclear cells (PBMC) by HIV-2 isolates have been attributed to the use of CCR5 or CXCR4." (PMID 35563157, 2022). "CXCR4 antagonist (plerixafor) was used in 5.6% (n = 3) of patients, which ameliorated the burden and frequency of infection and improved panleukopenia." (PMID 35947323, 2022). "Similar results were also found in Sebastiscus marmoratus and Epinephelus coioides; Grouper (E. coioides) CXCR4 is expressed in response to pathogens infection and early stage of development." (PMID 35287569, 2022). "Infection of MΦ by viruses using CXC chemokine receptor 4 (CXCR4) as a coreceptor (X4- and R5X4-tropic viruses) is less frequent, although reported." (PMID 35622876, 2022). "Collectively, the CXCL12/CXCR4 axis can have important pathophysiological roles in infection‐induced PTL." (PMID 35318804, 2022). "Expression of the CD74 co-receptor was found on ~50% of both ILC2s and peritoneal macrophages, and although downregulated by infection in the former population, many ILC2s expressed the combination of CXCR4 and CD74." (PMID 35288645, 2022). "Because of the more robust infection seen with CXCR4-tropic virus, subsequent experiments were performed using the CXCR4-tropic GFP reporter virus except when noted." (PMID 36420277, 2022). "Another approach that is of interest is the simultaneous knockout of CXCR4 and CCR5, rendering cells refractive to infection by both CXCR4- and CCR5-tropic strains." (PMID 35892930, 2022). "Knockout of CXCR4 (green dots), resulted in strong decreases in infection rates at all three timepoints, as did knock out of LEDGF and CDK9." (PMID 35365639, 2022). "While the high expressors preferentially undergo bystander cell death, presumably because high CXCR4 levels facilitate transfer of virus from productively infected cells, the low CXCR4 expressors are potentially more prone to undergo productive infection." (PMID 35784348, 2022). "In contrast, infection with the R5-tropic Envs JRFL and ZM-135 was more effectively inhibited by the variant MT-C34GPI, expressed either from proviral DNA or the CXCR4 locus, than by MT-C34-X4 (middle and right bars)." (PMID 35073736, 2022). "Luciferase assays performed 48 h after the coculture confirmed that cell-to-cell transfer of these CXCR4-using viruses led to infection of the target MDMs, which was significantly inhibited by T20." (PMID 35622876, 2022). "First, the CXCR4-tropic HxB2 virus was used, in which the nef cassette was exchanged for eGFP to allow visibility and quantification of infection events." (PMID 36230931, 2022).
infection (continued). "(D) Representative immunofluorescent staining images (left) and quantification (right) of CXCR4 (red) labeled MKs (blue) egressed into sinusoids (green) upon infection (n=46 CXCR4low MKs and 69 CXCR4high MKs in 4 biological replicates)." (PMID 35904250, 2022). "Throughout all stages of infection, the increase in the myelination pathway is driven by the genes Hexb, Tgfb1, and Cxcr4." (PMID 33816350, 2021). "The overexpression of LAPTM5 resulted in a 257- to 664-fold reduction in infection by CXCR4-, CCR5-, or dual-tropic Vpr-defective HIV-1, whereas the production of HIV-1 capsid was intact." (PMID 34140527, 2021). "We hence tested the ability of our H7 cell line to resist infection by CXCR4 and CCR5 tropic HIV isolates." (PMID 33516234, 2021). "In contrast, the lower the expression of CXCR4 at 1.5 months post-infection, the stronger the decline in MuV-specific T-cell frequencies observed (r = 0.7273, p = 0.0144)." (PMID 34960178, 2021). "We found pathogenic mycobacteria trigger the host to produce more miR-206 in order to suppress the otherwise protective recruitment of neutrophils to sites of infection via the host Cxcl12/Cxcr4 signalling pathway." (PMID 33826679, 2021). "Patients exhibit a decrease of their total count in the blood correlated with a decrease of CXCR4 MFI ratio, a decrease of CXCR4 and CD26 surface expressions and a higher CXCR4/CD26 ratio on the naive subset in the group with a history of severe infection." (PMID 34906163, 2021). "In this study we have demonstrated an in vivo link between infection-induced miR-206 expression and the Cxcl12/Cxcr4 signalling axis in the control of mycobacterial infection." (PMID 33826679, 2021). "In our study, we observed that vaginal epithelial cells did facilitate infection of sorted CD4+ T cell subsets enriched for co-receptors CCR5/CXCR4." (PMID 33816339, 2021). "Expression of CD4CAR resulted in successful infection of HOS CCR5 or HOS CXCR4 cells by R-5 tropic HIVNFNSXSL9 or X-4 tropic HIVNL4-3." (PMID 33793675, 2021). "The HOS-CD4-CCR5 cells supported X4-tropic HIV-1IIIB infection, as they expressed endogenously functional CXCR4." (PMID 34076481, 2021). "Increased transcription of Elmo1 following miR-206 knockdown is likely to increase neutrophil mobility during infection in cooperation with increased Cxcl12/Cxcr4 signalling." (PMID 33826679, 2021). "The infection of CEM‐GFP cells with CXCR4‐using virus, (HIV‐1 NL‐4.3) progressively increased GFP fluorescence over 5 days." (PMID 33793064, 2021). "CXCR4-using viruses can also interfere with the replenishment of naive cells through depletion of thymocytes and infection of CD34+ multipotent hematopoietic progenitor cells in the bone marrow (BM)." (PMID 33872329, 2021). "Explant infection was carried out using a CCR5 and CXCR4 HIV-1 variant, namely BaL and LAI, to account for potential differences in compound effect on virus as well as cytokine production associated with target cell tropism." (PMID 34835109, 2021). "Coreceptor targeting favored CCR5 over CXCR4 mainly because R5 tropic viruses are predominantly involved in the early viral transmission of infection, predominate in the asymptomatic stage of infection, and persist throughout all stages of the disease." (PMID 34276704, 2021). "In MOI 10, a similar pattern was repeated in 48 and 72 h P.I. In MOI 5, the amount of CXCR4 marker in infected cells and in healthy cells during indicated times of infection are expressed similarly at a high level." (PMID 33933086, 2021). "The effect observed in the double knockdown is consistent with a reduction in Cxcr4 and therefore the neutrophil response in infection via haematopoiesis and chemoattraction." (PMID 33826679, 2021). "To achieve this, we isolated CD4+ T cells, then pre-incubated activated CD4+ T cells with pEVs from HCs, HIV infected on ART or ART-naïve individuals before infection with the CXCR4-tropic HIV LAI virus." (PMID 34249000, 2021).